KRAS (KRas proto-oncogene, GTPase)
Diseases named in the same sentence as KRAS in open-access papers (continued):
Sharing a sentence is not in itself a finding about the gene and the disease.
tumor (continued). "Another study showed that the presence of a KRAS mutation in codons 12, 13, or 61 was the strongest predictor of poor local treatment outcome, with 1-year local control rates of 42.9% compared to 72.1% for tumours without detected mutations." (PMID 41226343, 2025). "Although KRAS G12C inhibitors show some efficacy when used alone, literature suggests that combination therapies may offer a promising direction for overcoming resistance and improving tumor suppression." (PMID 41200180, 2025). "The identification of genes linked to patient outcomes and immune components in the tumor microenvironment further underscores the notion that KRAS signaling does not operate in isolation but rather interconnects with immunological mediators, including macrophage-dependent processes." (PMID 40607411, 2025). "Notably, KRAS acts as a trigger to drive glucose metabolism, which promotes tumor proliferation." (PMID 41184283, 2025). "However, among the 13 patients with KRAS mutations in our study, none experienced tumor growth, and the pCR rate in patients undergoing surgery was 75% (6/8), which was comparable to the overall population and consistent with findings in the NICHE-2 study." (PMID 40818457, 2025). "Consequently, we postulate that the biological significance of KRAS-mediated activation of lysosomal function may be similar to that of cellular senescence, which serves as a mechanism suppressing tumor development." (PMID 40057469, 2025). "Moreover, KRAS-mutant cancer cells are prone to activating cancer-associated fibroblasts (CAFs) via MAPK and PI3K signaling, promoting desmoplasia and deposition of collagen around tumor clusters." (PMID 40809430, 2025). "Thus, the KRAS mutation status might be directly linked to TGF‐β1 responses, impacting on tumor aggressiveness and therapy response of patients." (PMID 40066744, 2025). "Therefore, even transient therapeutic response that drives tumor shrinkage in a defined subset of patients (patients with KRAS LOH) might offer a promising treatment opportunity and potential clinical benefit in the neoadjuvant setting." (PMID 39412982, 2025). "Furthermore, the broad antitumor activity across different tumor types with KRAS WT amplifications shown here in in vitro and in vivo preclinical models indicates the opportunity for a tumor agnostic approach of targeting KRAS WT–amplified tumors with our current clinical compound BI 3706674." (PMID 39711431, 2025). "As KRAS has been shown to suppress STAT1 transcription, we hypothesize that PTDSS1 loss impairs RAS signaling, which in turn releases the suppression of STAT1 expression, enhancing tumor cell responsiveness to IFN-γ in a cell-intrinsic manner." (PMID 40929270, 2025). "However, copper chelators (such as TTM) or ATP7A inhibition can reverse this mechanism, selectively inducing cuproptosis in KRAS‐mutant cells and significantly suppressing tumor growth, representing a potential precision therapeutic strategy for KRAS‐mutant CRC." (PMID 41152153, 2025). "This MHC-dependent mechanism enables TCR-T cells to recognize intracellular tumor-associated or tumor-specific antigens that are processed and presented via MHC molecules, such as cancer/testis antigens (e.g., NY-ESO-1 and MAGE-A4) and neoantigens derived from somatic mutations (e.g., KRAS G12D)." (PMID 40563595, 2025). "Additionally, we demonstrate that this method, when combined with syngeneic mouse tumor models, provides valuable insights into the guanine-nucleotide binding state of KRAS in tumor tissues and serves as an effective tool for evaluating the efficacy of KRAS/G12C inhibitors in vivo." (PMID 40286847, 2025).
tumor (continued). "Based on the fundamental roles of KRAS in cancer, understanding the correlation between KRAS and metabolic changes, such as the Warburg effect, mitochondrial metabolism, lipid metabolism, glutamine metabolism is vital for deciphering tumor biology and developing targeted therapies." (PMID 39806421, 2025). "In addition, KRAS alterations may promote recruitment of immunosuppressive cells and downregulate PD-L1 expression, resulting in changes in tumour microenvironment." (PMID 40652145, 2025). "Although a degree of variability in the fitness conferred by specific mutations of oncogenes is expected, for example, G12D variants compared with A146T in KRAS, that complete loss of the β-catenin–binding 20AARs in tumor-suppressive APC does not lead to maximal cancer risk is remarkable." (PMID 41091816, 2025). "Thus, ERK3 as a protein or its kinase activity could be a potential therapeutic target in the treatment of KRAS‐driven tumours." (PMID 39348153, 2025). "This phenomenon may be attributed to gefitinib-induced paradoxical activation of ERK1/2 in resistant cells through the MSI2-AGO2/miR-30a-3p-CGRRF1 regulatory axis, which subsequently activates the KRAS/ERK pathway to promote tumor progression and drug resistance." (PMID 41155547, 2025). "Furthermore, combining CALLY with molecular and genomic markers such as MSI, KRAS, and BRAF mutations, as well as circulating tumor DNA (ctDNA), could generate more comprehensive predictive models that align with the principles of precision oncology." (PMID 41479671, 2025). "Furthermore, RASON inhibition enhances the therapeutic efficacy of AMG-510, a KRASG12C inhibitor, suggesting that RASON targeting could exert anti-tumor effects alone or synergize with existing KRAS-directed therapies to improve treatment outcomes." (PMID 40128846, 2025). "Importantly, tumor cells from patients with EGFR mutation showed increased expression of several MHC class I and II genes compared to tumor cells from patients with KRAS mutant tumors, along with an increase in CD74, which regulates the presentation of MHC class II proteins." (PMID 39803458, 2025). "On the other hand, tumors with point mutations like KRAS or EGFR may follow a branched evolution, developing multiple subclones in parallel, each acquiring diverse passenger or even additional driver mutations over the course of tumor development." (PMID 40723270, 2025). "In CRC, proteomic analysis has demonstrated that downstream signaling molecules linked to KRAS mutations—such as proteins in the MAPK and PI3K-AKT pathways—show varying expression across different tumor subtypes, suggesting they could serve as promising new therapeutic targets." (PMID 40771479, 2025). "However, further changes in KRAS allelic states in PDAC during the evolution of tumors might follow distinct routes that are accompanied by the inactivation of tumor suppressors." (PMID 40227826, 2025). "Tumor site (proximal or distal, right-sided or left-sided) and stage (II or III) are independent prognostic indicators of CRC and may be confounders for our survival analysis of KRAS/BRAF mutations." (PMID 40279317, 2025).
tumor (continued). "Specifically, KRAS-mutant tumors exhibited decreased NRG1 expression and hyperactive SG formation, indicating that oncogenic mutations may intersect with subcellular organizational dynamics to sculpt tumor behavior." (PMID 41190067, 2025). "Unlike in the primary tumor situation, KRAS mutations were not only highly frequent in CMS3 metastases (58.33%) but to an even higher extent detectable in CMS1‐classified samples (66.67%) pointing towards potential metastasis‐specific alterations of KRAS mutation frequencies for CMS1." (PMID 39825568, 2025). "In S2, key pathways include KRAS signalling, myogenesis and mitotic spindle functioning, indicating that asprosin might affect cell cycle regulation, cancer-related signalling, and vascularisation, all of which are critical for tumour growth and progression." (PMID 40871563, 2025). "We selected KRAS, EGFR, BRAF, and MET mutations for inclusion in the multivariable model because they are among the most commonly altered driver mutations in LUAD and are known to significantly influence tumor behavior, prognosis, and response to targeted therapies." (PMID 40507306, 2025). "Similarly, a team from Memorial Sloan Kettering (MSK) did not associate KRAS mutation status with invasive disease or more aggressive tumour behaviour or advanced stage of disease." (PMID 39941911, 2025). "One could speculate that the measured KRAS protein not only represents the tumor cells." (PMID 40596921, 2025). "In addition, they demonstrated that the loss of KRAS mutations in lung-specific oligometastatic CRC further suggests a unique evolutionary trajectory, potentially linked to reduced aggressiveness or changes in the tumor microenvironment." (PMID 39806421, 2025). "Overall, 40.5% of patients with available primary tumor tissue had a BRAF mutation in their tumor tissue (35.1% BRAFV600E, 2.7% BRAFV600R, BRAFV600K 2.7%), 18.9% of patients had a NRAS mutation (10.8% NRASQ61R, 8.1% NRASQ61K) and one patient (2.9%) had a KRAS mutation (KRASG12) in their tissue." (PMID 40652269, 2025). "Interestingly, BRAF and KRAS mutations are mutually exclusive, meaning that they typically do not occur together in the same tumor." (PMID 40429703, 2025). "However, in KRAS‐mutant tumours, the STING pathway is frequently suppressed." (PMID 40596709, 2025). "Increasing evidence suggests that identification of such combinatorial strategies aiming at synthetic lethality with oncogenic KRAS inhibition might be highly tissue-specific and vary with individual sites of tumor origin and with individual patterns of accompanying oncogenic genomic variants." (PMID 38892436, 2024). "It has been found using a genome-specific CRISPR-Cas9 knockout screen that specific metabolisms are affected only when KRAS is active on cells, which may have future therapeutic benefits for cancer metabolism in a patient's mutant KRAS tumor, exhibiting some therapeutic application." (PMID 39467702, 2024). "In addition, KRAS inhibition endowed tumors with a remarkable increase in anti-tumor immunity." (PMID 38216551, 2024). "No KRAS nor BRAF variants were detected in EGFR-positive tumor samples." (PMID 39063150, 2024). "Consequently, a tumor majorly characterized by KRAS-mutant clones at diagnosis may become mostly KRAS wt." (PMID 39682112, 2024). "Meanwhile, the inhibition of KRas‐induced cancer progression in mice with lung cancer after gene knockdown, and the reduction in respiratory chain complex biosynthesis, demonstrated the absolute requirement of mitochondrial respiratory chain proteins for tumor cell progression." (PMID 39584783, 2024). "However, targeting TBK1 in tumor cell lines harboring KRAS mutations failed to significantly impede tumor growth." (PMID 39161768, 2024).
tumor (continued). "The differential enrichment of KRAS signaling between NMP and metastatic potency (MP) organoids may reflect that while KRAS activation is necessary for tumorigenesis, its role in metastasis could be modulated by other genetic or epigenetic factors present in the tumor microenvironment." (PMID 38619751, 2024). "Notably, not all patients with KRAS mutations benefit from ICIs, largely because of tumor heterogeneity-a consequence of co-occurring genomic alterations." (PMID 38291516, 2024). "Tumors with KRAS 12/13 mutations may exhibit a more aggressive tumor phenotype potentially due to the significant association of ADAM8 with the formation of distant metastases and the invasion of the tumor environment." (PMID 39329961, 2024). "Notably, KRAS mutant cases with high POM121 protein positivity had more PPARγ protein localized to the peri-nuclear and cytoplasmic regions of the tumor cells compared with KRAS wt cases, who showed nuclear positivity of PPARγ (n = 208, *p < 0.05, Fisher Exact test)." (PMID 38177114, 2024). "Therefore, KRAS mutant tumors are especially immune-excluded, and therapeutic approaches aimed at activating anti-tumor immune program might be essential to eliminate the disease." (PMID 38216551, 2024). "The splenic flexure tumor was also KRAS mutated, but the cancer in the rectosigmoid was not." (PMID 39516274, 2024). "Also, metabolic conversion of lipids in the high-fat diet into bioactive molecules may enhance KRAS signaling and/or limit DNA repair in tumor cells." (PMID 38672675, 2024). "Several studies have shown that in NSCLC cells with gene alterations of KRAS G12C, BRAF V600E, EGFR, ALK, or ROS1, dysregulation of the Hippo pathway decreases the initial response to various tyrosine kinase inhibitors, which is associated with resistance of targeted therapy and tumor recurrence." (PMID 38499647, 2024). "Because tumor‐associated axonogenesis, which manifests as increased nerve density, represents the initial step that drives neuroplasticity and PNI, we conducted further analyses to determine whether KRAS is involved in axonogenesis in PDAC." (PMID 39488792, 2024). "For example, in this study, it was observed that the overexpression of this miRNA is associated with the survival of PC and that its expression negatively correlates with the expression of KRAS, so that, in PC, this miRNA may possibly play a tumour suppressor role by directly regulating this gene." (PMID 39057123, 2024). "Although oncogenic KRAS pathway reactivation will re-engage proliferative signaling, we postulated that restoration of KRAS-mediated immunosuppression may also contribute to tumor relapse." (PMID 38635884, 2024). "MiR-96 may act as a tumor suppressor, inhibiting the KRAS-signaling pathway." (PMID 38790924, 2024). "This suggests that the presence of KRAS mutations might play a role in tumor differentiation and may not be a strong determinant of tumor invasion and metastasis, indicating that other factors might contribute more substantially to metastatic potential." (PMID 38465160, 2024). "RMC-7977 caused tumour growth inhibition and induced multiple tumour regressions across a larger panel of 15 PDAC, CRC and NSCLC CDX and patient-derived xenograft (PDX) models bearing KRASG12X mutations and co-mutations representative of the genomic landscape of patients with KRAS-mutant cancers." (PMID 38589574, 2024). "Furthermore, the recent association observed between CD44 and KRAS-dependent carcinomas and the potential correlations between CD44 and tumor mutational burden (TMB) and microsatellite instability (MSI) open new research scenarios for developing new strategies in cancer treatment." (PMID 38672650, 2024).
tumor (continued). "To determine whether targeting of TF or mTORC2 in KRAS inhibitor-resistant tumor cells could influence macrophage polarization in vitro, we performed a cell-based assay where mouse bone marrow-derived macrophages (BMDMs) were incubated with conditioned medium (CM) of HCC44 or H1792 cells." (PMID 38191673, 2024). "Many of these genes are closely related to KRAS, so it is to be expected that the dysregulation of this miRNA could be involved in PC tumour promotion by suppressing the expression of genes related to cell proliferation or allowing the expression of those that promote tumour progression." (PMID 39057123, 2024). "These variables include age, diameter of the largest CRLM tumor, number of tumors, carcinoembryonic antigen (CEA) level, T category of the primary tumor, primary lymph node involvement, primary tumor side, presence of extrahepatic disease, surgical margin status, and KRAS mutational status." (PMID 39711552, 2024). "Furthermore, it was observed that the expression of this miRNA positively correlates with the expression of KRAS, so this miRNA could play a role in tumour promotion in PC, somehow repressing the expression of genes that suppress cell growth in PC." (PMID 39057123, 2024). "Further, our results raise the intriguing possibility that YAP1 antagonism may represent a therapeutic approach to counter anti-PD-1 therapy resistance in STK11-null, KRAS-driven LUADs by modulating tumor-intrinsic gene expression to promote a “hot” tumor immune microenvironment." (PMID 37968341, 2024). "Finally, our findings emphasize the significance of exploring the diverse aspects of tumor biology, particularly the immune system, regulated by mutant KRAS to create logical combinations that could produce durable patient responses." (PMID 39567998, 2024). "Moreover, KRAS mutations may create a favorable TME for gut microbiota, inducing carcinogenic bacteria to colonize within the tumor." (PMID 39523457, 2024). "GSVA of the single-cell data showed that tumor cells with a high Disulfidptosis-Related Score (DRS) had increased activity in pathways associated with malignant phenotypes, such as TGF Beta signaling, EMT, inflammatory response, KRAS signaling, Notch signaling, and Wnt/β-catenin signaling." (PMID 38862242, 2024). "Indeed, the abundance of the targeted KRAS G12V peptide/HLA complex on the surface of in vitro–cultured tumor cells in this study was variable, often between four and 242 copies per cell even in cell lines that were engineered to constitutively express the restricting HLA molecule." (PMID 39484723, 2024). "Whether the timing of high calorie diet is important for tumor development and the exact underpinning mechanisms remain to be investigated, however, ER chaperones are unveiled as an attractive way to selectively target KRAS-driven lung tumors." (PMID 36675307, 2023). "Finally, a unique advantage to covalently modifying the mutant KRASG12C protein with an inhibitor is the potential to specifically target drug-modified KRAS epitopes with antibodies or cell therapies, precisely flagging KRAS-mutant tumour cells for immune-mediated destruction." (PMID 36864508, 2023). "Furthermore, KRAS G12C targeting BiTEs can also recognize tumor cells that are resistant to KRAS inhibition provided that drug engagement is maintained and therefore could be used to overcome targeted therapy resistance." (PMID 37581538, 2023).